SPDYE10 (speedy/RINGO cell cycle regulator family member E10)
Synonyms: SPDYE10P
Tractability: No criterion of Open Targets' tractability assessment is met for any kind of drug.
Gene: Protein-coding gene on chromosome 7 (73,104,008 to 73,155,431, reverse strand). Ensembl gene ENSG00000274570.
Gene Ontology:
Molecular function: protein kinase binding
Genetic constraint (gnomAD): Loss-of-function variants: 0 observed, 3.8 expected, observed/expected ratio (o/e) 0, 90% interval 0 to 0.79. That is too few expected variants to judge how well the gene tolerates losing a copy. Missense variants: 2 observed, 54.71 expected, observed/expected ratio (o/e) 0.0366, 90% interval 0.014 to 0.12. Synonymous variants: 0 observed, 24.07 expected, observed/expected ratio (o/e) 0, 90% interval 0 to 0.12.
Homologues: Orthologues: rat Spdye4 (49% identical), mouse Spdye4a (48% identical), mouse Spdye4b (44% identical). Paralogues in human: SPDYE11 (100% identical), SPDYE17 (100% identical), SPDYE8 (100% identical), SPDYE9 (100% identical), SPDYE13 (99% identical), SPDYE14 (99% identical), SPDYE15 (99% identical), SPDYE12 (99% identical), SPDYE3 (89% identical), SPDYE18 (83% identical), SPDYE16 (83% identical), SPDYE2 (83% identical), and 6 more.